SUCLG2 (succinate-CoA ligase GDP-forming subunit beta)
Diseases named in the same sentence as SUCLG2 in open-access papers (continued):
Sharing a sentence is not in itself a finding about the gene and the disease.
SUCLG2 also shares sentences with these, for which no sentence is quoted: epilepsy (2 papers); paraganglioma (2); pheochromocytoma (2); Abdominal obesity (1); bacterial infections (1); bladder cancer (1); breast carcinoma (1); cardiomyopathy (1); cecum adenocarcinoma (1); cholangiocarcinoma (1); colon mucinous adenocarcinoma (1); diabetes (1); diabetic kidney disease (1); Epileptic encephalopathy (1); hearing loss (1); hepatocellular carcinoma (1); intestinal diseases (1); kidney disease (1); kidney failure (1); leukemia (1); lymphatic disease (1); mammary adenocarcinoma (1); mitochondrial disease (1); Obesity (1); ovarian carcinoma (1); Pan (1); Parkinson’s (1); prion disease (1); prostate adenocarcinoma (1); prostate tumor (1).
A further 4 diseases each share a sentence with SUCLG2 in 1 paper.